CAV1 (caveolin 1)
Diseases named in the same sentence as CAV1 in open-access papers (continued):
Sharing a sentence is not in itself a finding about the gene and the disease.
tumor (continued). "Caveolins(including CAV1) are essential for caveola formation, previous study has demonstrated that CAV1 is involved in mechanically regulating the extracellular environment as well as tumor metastasis and invasion." (PMID 33870858, 2021). "In CP, high proliferative activity and high-level expression of CD44 and CAV1 suggest a more aggressive tumor behavior." (PMID 33672734, 2021). "Several authors have suggested that when caveolin-1 is located in the nucleus, its role is related to tumor suppression and gene regulation." (PMID 33037799, 2021). "We also assessed stromal Cav-1 expression in tumor samples from core biopsies and surgical tumor samples." (PMID 34590611, 2021). "Several genes from the candidate gene-set with higher expression associated with higher 25-OHD are included in enriched GO ontology terms relevant to carcinogenesis and have reported tumour suppressor activity (e.g. FOXOs, CAV1, LRP1)." (PMID 34340708, 2021). "Specifically, female patients expressing high tumour levels of Cav-1 displayed a significantly shorter median survival time compared to male patients expressing high levels of Cav-1 (median survival 90.5 days vs 320 days: HR=3.145, P=0.0000015)." (PMID 34490102, 2021). "Irrespective of the staining assay, neither response to therapy or overall survival correlated with the expression level of Cav-1 in the stroma or tumor epithelium." (PMID 34813586, 2021). "Even within the same (p16-negative) tumor specimen, CAV1 immunoreactivity in epithelial cells was strongly increased in tumor cells with a less differentiated phenotype." (PMID 33868995, 2021). "The present study aimed to explore the clinicopathological significance and the respective biomarker potential of CAV1 expression levels, in both tumor cells and the stromal compartment that houses predominately the CAFs as well as vascular structures." (PMID 33868995, 2021). "In concordance, Abraxane’s tumor uptake was antagonized by inhibition of caveolar-mediated endocytosis, and the knockdown of Cav-1, the structural component of caveolae, also attenuated Abraxane’s anti-tumor properties in vivo." (PMID 34141613, 2021). "When the cells are under stress (such as starvation), knockout of CAV1 gene in MEFs can promote the formation of late autophagy lysosomes, enhance autophagic flux and promote cell survival, and it is involved in tumor progression." (PMID 34955837, 2021). "Cav1 expression was analyzed in 173 tumor samples and correlated to locoregional recurrence and overall survival." (PMID 34207120, 2021). "This is the case of CAV1, a protein located at MAMs that acts both as a tumor suppressor and a promoter of metastasis." (PMID 33718356, 2021). "Overall, closely positive correlation was observed between biomarker expression and tumor infiltration, especially for CAV1, CFD and FMO2." (PMID 33870858, 2021). "The CAV-1 is highly expressed in many tumors and executes an important role in tumor progression, and with a potential to transform the tumor microenvironment (TME) leading to poor treatment outcome." (PMID 34762666, 2021). "High expression for Cav-1 is particularly noted within hyperplastic blood vessels and microvasculature proliferations as well as within the tumours’ peri-necrotic and pseudo-palisading zones." (PMID 34490102, 2021). "For example, elevated levels of Cav-1 in clinical tumour tissue from prostate, bladder, kidney and multiple myeloma is unequivocally linked with metastasis and poor prognosis." (PMID 34490102, 2021). "A few studies have reported positive correlations between Cav-1 expression and increased tumour histological grade." (PMID 34490102, 2021). "The understanding of Cav-1 biology in GB is similarly controversial, with some reports suggesting Cav-1 to be a tumour suppressor and others supporting the oncogenic function." (PMID 34490102, 2021). "In cancer, CAV1 operates as both a tumor suppressor gene and a promoter of metastasis, depending on the cancer type and stage." (PMID 35008571, 2021).
tumor (continued). "High Cav-1 expression correlated with other factors associated with poor prognosis: IDH w/t status, high histological tumour grade and low KPS score." (PMID 34490102, 2021). "For both tumor and benign ovarian tissue, higher expression of Cav-1 was observed in the epithelial regions as compared to stromal regions." (PMID 34813586, 2021). "Upon tumor progression, CAV1 levels strongly increase in malignant epithelial cells, which was correlated with worse clinical outcomes in a couple of cancer entities, including prostate, pancreatic, and lung cancer." (PMID 33868995, 2021). "How Cav1 overexpression affects the response to treatment and tumor evolution is only sparsely documented in HNSCC." (PMID 34207120, 2021). "In agreement with our PDX samples, we found that tumor tissue cores from patients with CR possessed higher caveolin-1 positivity and lower Sox-2 positivity than those from patients with PD." (PMID 34546978, 2021). "Recent gene expression data has shown Cav-1 to be one of the top genes upregulated in the invasive GB phenotype and especially so in tumours with a marked mesenchymal signature." (PMID 34490102, 2021). "The results have shown that the median level of caveolin-1 (n = 15), was approx. 950 pg/ml almost two-fold higher in tumor bearing animals as compared to control animals (450 pg/ml)." (PMID 34762666, 2021). "CAV1-expressing fibroblasts are abundant in the tumor stroma of multiple cancer types, including CRC, and stromal CAV1 expression is associated with a poor prognosis." (PMID 34681633, 2021). "Conformingly, we provide further and new evidence that the characteristic shift in stromal‐epithelial CAV1 being functionally relevant to tumor progression even occurs in penile SCC." (PMID 33868995, 2021). "Pre-clinical studies have shown that Cav-1 is critical for the uptake of albumin as well as nab-paclitaxel in PDAC cells, causing a subsequent apoptotic response in tumor cells in vitro." (PMID 34590611, 2021). "Cav-1 expression was evaluated by immunohistochemistry staining in neoplastic and stromal cells, using metastatic sites or primary tumor tissue specimens." (PMID 34590611, 2021). "In summary, CAV1 at the plasma membrane participates in a large number of signaling events that contribute to its role both as a tumor suppressor and promoter of metastasis." (PMID 32458269, 2020). "Taken together these results suggest that one potential mechanism, by which CAV1 expression exerts its tumor suppressor activity, is by forming protein complexes with UPR sensors in the ER." (PMID 32811828, 2020). "Because of the heterogeneity of Cav-1 expression in different tumors, therapies targeting Cav-1 will need to consider the specific roles or functions of this protein within the corresponding type of tumor cell." (PMID 32528105, 2020). "In summary, we conclude that tumor suppression by CAV1 in the cytosol is attributable at least in part to attenuation of the UPR, and identified S80 as an essential residue in this context." (PMID 32811828, 2020). "For many human tumors, CAV-1 upregulation influences cancer cell survival and growth, thus favoring tumor progression." (PMID 32733649, 2020). "Silencing of CAV1 in cancer cells themselves was already shown to re-sensitize tumor cells to RT-induced apoptosis." (PMID 32273493, 2020). "These functions of CAV1 in vitro are consistent with the notion that its activity as a tumor suppressor in vivo should require the expression of E-cadherin." (PMID 32825247, 2020). "Overall, these results indicate that CAV1 displays properties characteristic of a tumor suppressor in a variety of cellular models." (PMID 32811828, 2020). "We also found that in patients with NF1-MPNST with lung metastasis, MSI2 was highly expressed in comparison to primary tumours, where CAV1 expression was the opposite; CAV1 expression was low in lung metastases and high in primary tumours." (PMID 32606289, 2020).
tumor (continued). "CircCCDC9 functions as a tumor suppressor in inhibiting the progression of GC through miR-6792-3p/CAV1 axis, which has provided an exploitable biomarker and therapeutic target for patients with GC." (PMID 32386516, 2020). "All together, these data identify a role for CAV1 in the formation of EVs that specifically favor tumor development, progression, and conditioning of the metastatic niche, although the mechanisms by which this occurs remain to be determined." (PMID 32458269, 2020). "We conclude that the tumor suppression by CAV1 involves the attenuation of the UPR, and identified S80 as essential in this context." (PMID 32811828, 2020). "As indicated, CAV1 has been reported to function both as a tumor suppressor and as a promoter of tumor progression and metastasis." (PMID 32458269, 2020). "The network associated with regulation of tissue invasion by tumor cell lines and lipid export was connected by five proteins: ACAT1, CAV1, CTSS, S100A12, and S100A9." (PMID 33607292, 2020). "In general, bleomycin can modulate Cav-1 expression, give rise to cell senescence and act as an anti-tumor agent." (PMID 31991790, 2020). "CAV1 plays a dual role in tumour progression, and it can inhibit or induce tumour progression depending on the tumour type." (PMID 32606289, 2020). "The promoter CpG hypermethylation of CAV1 occurred at the onset of tumor development though a hypermethylated state remains in full‐blown tumors." (PMID 32508059, 2020). "Cav-1 has been reported to positively and negatively impact tumor growth through tissue-specific functions." (PMID 32633727, 2020). "However, the mechanisms underlying caveolin-1-mediated tumor progression remain unclear." (PMID 32676485, 2020). "The positive or negative effects of Cav‐1 vary among a variety of aspects of tumor progression, due to the direct or indirect interaction of Cav‐1 with effector molecules to affect caveolae's function." (PMID 32508059, 2020). "As a consequence of cancer-related studies, Cav-1 and -2 have been investigated as tumor prognostic markers for different types of cancers, mostly carcinomas." (PMID 33195223, 2020). "IHC assays also demonstrated that upregulation of circCCDC9 enhanced the expression of CAV1, E-cadherin and weakened the expression of β-catenin, cyclin D1 and Ki-67 in xenograft tumor tissues." (PMID 32386516, 2020). "The correlation among CAV-1, VEGF levels, and microvessel density has been observed, indicating that CAV-1 plays a role in tumor angiogenesis with VEGF." (PMID 32357558, 2020). "Although previous studies have mainly focused on delineating the function of Cav-1 in cancer cells, recent studies have started to emphasize the function of the Cav-1 protein in the tumor microenvironment." (PMID 32377291, 2020). "Initial reports highlighted caveolae and caveolin downregulation in transformed cells, and murine Cav-1 and 2 genes were mapped to a tumor suppressor locus." (PMID 33195223, 2020). "Although oncogenic properties of Cav-1 have been demonstrated in BCa, evidence suggests a tumor suppressive role of Cav-1 in BCa." (PMID 32633727, 2020). "It has been reported that CAV1 acts not only as a tumour suppressor but also as a promoter of metastasis." (PMID 32606289, 2020). "The importance of CAV1 in lipid transport is well-established, but again more research on the regulation of these processes and their relevance to tumor biology is necessary." (PMID 32458269, 2020). "Taken together, these results indicate that inhibition of NOS activity is likely to be responsible for reduced HIF1α activity and hence tumor suppression by CAV1." (PMID 32825247, 2020). "ZO-1 exhibited a continuous distribution at the edges of ECs, while caveolin-1 was expressed in the cytoplasm in tumor tissues." (PMID 32116702, 2020).
tumor (continued). "Among the significantly regulated proteins, several presented a link with membrane domains, like, for instance, the monocarboxylate transporter (MCT4; SLC16A3), whose expression was found to relate to that of caveolin-1 in tumor stroma." (PMID 32244540, 2020). "(2018) further specified that higher tumor Cav-1 levels and lower stromal Cav-1 levels were significantly associated with longer progression free survival of metastatic breast cancer patients receiving Nab-PTX in combination with gemcitabine." (PMID 31858848, 2020). "Caveolin-1 (Cav-1) is the essential structural protein of caveolae, and acts as a tumor suppressor by regulating the signaling transduction associated with the cell proliferation, differentiation, invasion, adhesion, apoptosis and metastasis." (PMID 32117718, 2020). "The two first mentioned roles of CAV1 are affected by the presence of the glycoprotein E-cadherin, which enhances CAV1 function as a tumor suppressor and blocks the ability of CAV1 to promote metastasis in vivo." (PMID 32152405, 2020). "The effects of caveolin-1 overexpression in various types of invasive tumor cells have also been investigated." (PMID 32676485, 2020). "This dual role has been found to be stage-dependent, since Cav-1 is downregulated and performs tumor-suppressor function at the early stage, while at the later stage, Cav-1 is up-regulated and plays oncogenic roles." (PMID 31991790, 2020). "Caveolin-1 (Cav-1) is a scaffold protein of plasma membrane caveolae that acts as a tumor modulator by interacting with several cell signals." (PMID 32117718, 2020). "Recent study indicated that stromal CAV1 favors tumor invasion and metastasis through force-dependent architectural regulation of the microenvironment." (PMID 32401768, 2020). "Recent studies indicate that CAV-1 has several other functions beyond protein transport like its role in signal transduction, tumor progression and tumor regression and also that KRAS inhibits MTH1 function through CAV-1." (PMID 31919461, 2020). "Tumor sections were analyzed by immunohistochemistry and stained for VEGF to identify in vivo differences in angiogenesis caused by decreased caveolin-1 expression." (PMID 32676485, 2020). "Taken together, the evidence provided so far identified CAV1 as a secretable protein present in small lipoprotein structures that favor tumor development." (PMID 32458269, 2020). "A clinicopathological test has unveiled that Cav-1-positive lung AC patients tended to have worse tumor, node, and metastasis (TNM) stage in comparison to the negative patients." (PMID 31991790, 2020). "In general, Cav-1 has been reported to have both tumor-promoting and tumor-suppressive functions and is pro- or antisurvival depending on the cancer cell type." (PMID 32377291, 2020). "CAV1 is considered a key regulator of mitochondrial function that is important for its role as a tumor suppressor during cancer development." (PMID 32458269, 2020). "After 6 weeks, caveolin-1 siRNA-expressing SMMC7721 cells generated an average splenic tumor mass that was approximately 2 times less compared to negative control SMMC7721 cells." (PMID 32676485, 2020). "Downregulated CAV1 promotes glycolysis in adjacent cells leading to increased tumor growth via the reverse Warburg effect." (PMID 33108391, 2020). "Even in PCa, which is characterized by increased CAV1 expression levels in malignant epithelial cells at advanced, more radio-resistant disease stages, a reduction of CAV1 was suited to achieve tumor cell radiosensitization." (PMID 32273493, 2020). "In esophageal squamous cell carcinomas and pancreatic ductal adenocarcinomas, caveolin-1 overexpression correlates with a high histological grade, an advanced tumor stage and metastasis." (PMID 32676485, 2020). "Cav‐1 was identified to modulate the secretion of interleukin‐6 (IL‐6), which is an important factor in the microenvironment of tumor and the growth of cancer cells." (PMID 32508059, 2020).
tumor (continued). "Caveolae are a subset of lipid rafts characterized by the presence of caveolin-1, a known mediator for tumor progression and resistance to standard treatments." (PMID 32850408, 2020). "For example, CAV1 has been considered as a tumor suppressor gene in SCLC, whereas in NSCLC, CAV1 acts as an oncogene and is responsible for survival and growth of tumor cells." (PMID 32508059, 2020). "In contrast, the CAV1 IHC score in the primary tumour was significantly higher than it was in the lung metastases." (PMID 32606289, 2020). "As well, in later stages of cancer, the expression of CAV1 increases and favors the development of cellular characteristics related to enhanced malignancy, promoting tumor cell progression, invasion and metastasis." (PMID 32811828, 2020). "Previous work from our laboratory showed that E-cadherin and CAV1 synergize in suppressing subcutaneous tumor formation by B16F10 cells in syngeneic C57BL/6 mice." (PMID 32152405, 2020). "CAV1 expressing exosomes increased in the case of tumor resection and decreased after a week post-resection." (PMID 32759810, 2020). "To mimic the human situation we performed subcutaneous transplantations onto the hind limb of NMRI nude mice by injecting CAV1-silenced PC3(-) tumour cells in combination with control-transfected or TRIAP1-GFP-expressing WPMY-1 prostate fibroblasts." (PMID 30871022, 2019). "In view of such evidence, it is clear that CAV1 displays characteristics of a tumor suppressor, particularly in early stages of tumor development, although the precise mechanisms are often not well-defined." (PMID 31362353, 2019). "Mevalonate supplementation demonstrates that cholesterol is important for Cav1 expression in tumor cell survival." (PMID 31534543, 2019). "It has been reported that the disruption of Src-1 gene suppresses tumor progression, while the disruption of Cav-1 showed reverse effects." (PMID 30781353, 2019). "The longer tumor latency of Cav1 WT tumors relative to Cav1 Y14F tumors also support a role for pCav1 in early stages of growth." (PMID 31803361, 2019). "Control experiments in HER2-positive/CAV1-positive NCI-N87 gastric xenografts demonstrated that the tumor uptake of a radiolabeled isotype control IgG was significantly low and comparable in both saline-treated mice as well as those treated with lovastatin." (PMID 31171598, 2019). "CAV1/3 and KCNH2 were enriched in this term; the CAV1 gene is thought to function as a tumor suppressor or modifier gene in mammary epithelia." (PMID 31569550, 2019). "Taken together, this evidence led to a model suggesting that CAV1 plays a dual role in cancer, behaving as a tumor suppressor in early stages of cancer, but as a tumor promoter in advanced and metastatic stages." (PMID 31362353, 2019). "The expression of Cav-1 is distinct in different cell types and tissues and also in different stages of tumor, so the levels of Cav-1 mRNA and protein are valuable to be discussed in gynecological tumor." (PMID 31759347, 2019). "The reported tumor-promoting and tumor-suppressive functions of Cav1 are likely due to cell-specific effects, physiological context, and cancer stage." (PMID 31845647, 2019). "In vitro studies have shown that accumulation of CAV1 in tumour microenvironment in in tongue squamous cell cancer had a negative prognostic value." (PMID 30917536, 2019). "Reduced CAV-1 expression is associated with increased glycolysis and reduced mitochondrial function and this decrease in CAV-1 expression is thought to be mediated by tumor cell oxidative stress induced autophagy." (PMID 31426364, 2019). "In NSCLC, Cav-1 expression was higher in secondary lesions than in primary tumors, as the histology-related tumor aggressiveness increased." (PMID 31297035, 2019). "CAV1-dependent stromal-epithelial crosstalk in tumours with the potential to induce resistance includes processes such as autophagy or the ‘reverse Warburg effect’." (PMID 30871022, 2019).